AR (androgen receptor)
Diseases named in the same sentence as AR in open-access papers (continued):
Sharing a sentence is not in itself a finding about the gene and the disease.
ovarian carcinoma (100 papers, 2002 to 2026). A malignant neoplasm originating from the surface ovarian epithelium. "Strengths of our study include the unique classification and comparison of AR, ER, and PR in each diagnostic category of ovarian cancer." (PMID 40392873, 2025). "The goal of this study was to investigate AR expression among different types of OCs and stratify our results, as well as those of others, using the ovarian cancers diagnostic categories according to the recent WHO classification of GYN tumors." (PMID 40392873, 2025). "Fisher’s Exact test yielded a significant p-value of 0.01 when the AR positivity, in all diagnostic categories, was compared to the recurrent ovarian cancers, meaning AR had been expressed in the cancers beyond those with recurrence." (PMID 40392873, 2025). "This restoration decreases the expression of critical functional molecular markers such as CSF1R and AR, which are potentially associated with an elevated risk for ovarian cancer." (PMID 39622842, 2024). "miR-449a and miR-449b-5p suppression of CSF1R and AR expression as a link to flutamide action and ovarian cancer risk reduction." (PMID 39622842, 2024). "We previously assessed the expression levels of ER-α, ER-β, AR, GR, and PR in ovarian cancer tissues and determined their association with the survival rate." (PMID 36969037, 2023). "AR has been found to be associated with the occurrence, progression, prognosis, and drug resistance of ovarian cancer, endometrial cancer, and cervical cancer." (PMID 36193491, 2022). "The presence of AR associated with MMP-2 in the tumor cells was a risk factor for overall survival in epithelial ovarian cancer." (PMID 32718331, 2020). "Specifically, androgen receptor activation appears to be associated with increased risks of developing ovarian cancer and inducing tumor progression." (PMID 30791431, 2019). "Clinical or epidemiological studies have revealed the relationship between the risk of ovarian cancer and the level of serum androgens, treatment with androgenic/anti-androgenic drugs, or AR CAG repeat polymorphisms." (PMID 30791431, 2019). "A number of studies have addressed the association between CAG repeat polymorphisms of the AR gene and ovarian cancer risk." (PMID 27741511, 2017). "KLK4 expression is known to correlate with prostate and ovarian cancer, and AR signaling in association with TGF-β signaling is well-studied in these tissues/cells." (PMID 29249975, 2017). "This should be the first study to examine the association between AR repeat length polymorphisms and ovarian cancer risk in a relatively large group of Asian women." (PMID 26556855, 2016). "Protein kinase C related kinase 1 (PRK1) is a component of Rho-GTPase, androgen receptor, histone demethylase and histone deacetylase signaling pathways implicated in prostate and ovarian cancer." (PMID 25111382, 2014). "Consistent with this process, women who inherited a shorter repeat of the CAG segment of the androgen receptor allele presented with an earlier age of incidence of ovarian cancer, roughly about 7.2 years earlier compared to a control group." (PMID 22151998, 2011). "It has been reported that AR is an important marker in ovarian cancer, however, the molecular mechanisms for AR associated aggressive ovarian cancer behavior are still poorly understood." (PMID 22022581, 2011). "Our findings also highlight the need for further studies investigating the influence of both lifestyle-related and genetic factors in relation to ovarian cancer risk in general and to AR-defined subtypes in particular." (PMID 20565760, 2010). "In addition, the presence of CAG repeats in the androgen receptor (AR) gene was observed to increase the risk of ovarian cancer in the African American group." (PMID 33182707, 2020).
ovarian carcinoma (continued). "Research involving prostate and ovarian cancer propose the potential role of androgen receptor-coregulators, especially ARA70 (androgen receptor-associated protein 70), which seems to be necessary for both androgen receptor (AR) and VDR transcriptional activity." (PMID 31509973, 2019). "Even though ovarian cancer has a complex network and microenvironment, this phenomenon may mean that increased AR activity is related to a high risk of this disease." (PMID 29716628, 2018). "In summary, while AR alleles could be a useful ovarian cancer prognosticator under certain circumstances, the ovarian cancer subtypes and/or pathological conditions where it may best apply need to be further elucidated." (PMID 27741511, 2017). "In a previous study, AR status has been reported to be associated with a prolonged ovarian cancer specific survival, underlining its favourable prognostic role, but our paper, for the first time, describe its predictive value in the subgroup of EOC metastatic to the brain." (PMID 28467804, 2017). "In females, a shorter CAG repeat length in the AR gene is associated with ovarian cancer." (PMID 22151998, 2011). "It will be of great interest to determine in future studies whether the levels of ER, AR and p44 expression are associated with specific histological types of ovarian cancer, tumor grade, stages, and survival." (PMID 22022581, 2011). "Thus, there may be a complex reciprocal regulation between AR signaling and IL-6/IL-8 during the carcinogenesis of ovarian cancer and further study is necessary to elucidate the underlying mechanisms." (PMID 27741511, 2017). "Furthermore, shorter AR CAG repeats length and increased AR activity are associated with increased ovarian cancer risk and may be a useful prognosticator under certain circumstances." (PMID 27741511, 2017). "However, two studies found that longer CAG repeats of the AR gene could increase the risk of ovarian cancer." (PMID 27741511, 2017). "Accordingly, enhanced activity of AR and the transcription factors through crosstalk of their pathways may cause genomic instability or metabolic changes via overexpression of target txr genes, resulting in drug resistance phenotype in ovarian cancer cells." (PMID 26318424, 2015). "Since this discovery, the literature has shown that the androgen receptor (AR) acts as a key driver of Paclitaxel resistance in ovarian cancer." (PMID 40968783, 2026). "In contrast, no significant results have been reported from clinical trials, with initial studies showing limited benefit of AR blockade in ovarian cancer except for a subset of these patients who benefited from androgen deprivation therapy." (PMID 40392873, 2025). "Flutamide also increased miR-449a and miR-449b-5p levels in cancer cell lines leading to reduction of the AR protein levels and colony stimulating factor 1 receptor, both of which contribute to ovarian cancer progression." (PMID 40392873, 2025). "Experimental, preclinical studies have shown increased cell proliferation and division of AR-expressing epithelial ovarian cancer cells in tissue culture with androgenic stimulation and the opposite effect with androgenic inhibition." (PMID 40392873, 2025). "Larger prospective studies and clinical trials are necessary to establish the therapeutic effects of the anti-androgen/anti-AR agents on ovarian cancers." (PMID 40392873, 2025). "The involvement of the androgen receptor (AR) pathway in developing epithelial ovarian cancer is increasingly acknowledged." (PMID 39622842, 2024). "Sexual steroid hormone receptors play a significant role in ovarian cancer, especially EC, which usually presents with a higher frequency of positive results for androgen receptor (AR), estrogen receptor alpha (ER), and progesterone receptor (PR)." (PMID 39677071, 2024). "The Cancer of the Ovary Abiraterone trial (CORAL) was designed to investigate AR-targeted agents in ovarian cancer." (PMID 39598525, 2024).
ovarian carcinoma (continued). "Consistent with CSF1R and AR pathways being known contributors to ovarian cancer progression and initiation and being significantly elevated in HR women, we observed that miR-449a and miR-449b-5p reduced the migration of ovarian cancer cells." (PMID 39622842, 2024). "In vitro studies suggested that AR activation is related to the induction of tumorigenesis and cancer progression as well as chemoresistance in ovarian cancer." (PMID 38534733, 2024). "AR staining was unrelated to histopathological/clinical features in 157 endometrial carcinomas and in 221 ovarian carcinomas." (PMID 38790919, 2024). "Together, our findings underscore the potential involvement of cellular pathways such as CSF1/CSF1R and AR in the development of epithelial ovarian cancer and the response to flutamide treatment." (PMID 39622842, 2024). "miR-449a and miR-449b-5p repress AR expression at both the mRNA and protein levels in ovarian cancer cells." (PMID 39622842, 2024). "In the literature, AR regulates ovarian cancer stem cells by regulating Nanog that is a regulator of cancer stem cells pluripotency and self-renewal." (PMID 37046723, 2023). "A model that estimates the likelihood of ovarian cancer with the best association with outcomes was developed with nine proteins (P38MAPK, RAB11, FOXO3A, AR, BETACATENIN, Sox2, IGFRb, AKT_pS473, and ERCC5) using a LASSO–Cox algorithm." (PMID 37189432, 2023). "As has been highlighted by scholars, ovarian cancer cell proliferation can also be mediated by the androgen/AR-independent activation of PI3K/AKT." (PMID 37189432, 2023). "The mechanism studies revealed that the p-AKT expression in the ovarian cancer tissue was increased compared to the para-cancerous tissues, following a pattern similar to the increase of AR expression." (PMID 33613770, 2021). "In summary, our results suggested that the AR expression was significantly increased in ovarian cancer tissues, particularly in low-grade EOC, and the presence of high AR expression often suggested a worse prognosis." (PMID 33613770, 2021). "Although AR, ER, and PR are widely expressed in every histologic subtype of ovarian cancer, their distribution varies significantly by histology." (PMID 33891016, 2021). "Here, we found that the expression of AR, ER, and PR predicted survival and platinum sensitivity of ovarian cancer." (PMID 33891016, 2021). "Next, we investigated the potential mechanism of androgen/AR-induced proliferation observed in ovarian cancer cells." (PMID 33613770, 2021). "Androgen receptor agonists have been shown to induce migration and invasion in vitro in a variety of cell lines including ovarian cancer cells." (PMID 33923536, 2021). "Next, we showed that testosterone was able to promote the proliferation of ovarian cancer cells through activating the PI3K/AKT signaling pathway in an AR-dependent manner." (PMID 33613770, 2021). "The effects of AR, ER, and PR on survival and platinum sensitivity of ovarian cancer were evaluated using online databases." (PMID 33891016, 2021). "There is currently an ongoing Phase II study evaluating the use of enzalutamide on AR+ ovarian cancer (NCT01974765)." (PMID 33923536, 2021). "The androgen receptor (AR) is expressed in 43–90% of epithelial ovarian cancers with serous cancers being more likely to be AR positive when compared to non-serous." (PMID 33923536, 2021). "Our study suggested that androgen played an important role in cell proliferation in ovarian cancer cells in an AR-dependent manner." (PMID 33613770, 2021). "Blocking ERK phosphorylation has been shown to reduce AR gene transcription, and it has been demonstrated that pERK is necessary for androgen-induced proliferation of ovarian cancer cell lines OVCAR3 and SKOV3 cells." (PMID 33923536, 2021). "In the current study, we showed that the AR was stained positive in 67.1% of ovarian cancer tissues, which was significantly higher than that in para-cancerous tissues (29.4%)." (PMID 33613770, 2021).
ovarian carcinoma (continued). "The expression of the AR protein in ovarian cancer cell lines was determined by cell immunofluorescence and western blot." (PMID 33613770, 2021). "Using an intensity multiplied by area scoring system, we found a wide range of AR expression in the ovarian cancers (Figure." (PMID 34926721, 2019). "In this section, we describe epidemiological/clinical and preclinical observations indicating the potential involvement of AR signaling in ovarian cancer progression." (PMID 30791431, 2019). "All of these studies have thus demonstrated in vitro and in vivo data indicating that androgens promote cell proliferation/invasion of ovarian cancer via the AR pathway." (PMID 30791431, 2019). "Recently, a phase II study is being conducted to assess the efficacy of enzalutamide in women with AR-positive ovarian cancer (NCT 01974765)." (PMID 30791431, 2019). "As this read-out represents only one promoter, we also adapted the “AR activity score” for use in the ovarian cancer cell lines." (PMID 34926721, 2019). "Further research is thus required to precisely determine the functional role of AR signaling in ovarian cancer." (PMID 30791431, 2019). "PCR-based methods have detected AR gene expression in some primary cell cultures derived from human ovarian cancer and established human ovarian cancer cell lines, such as OVCA3." (PMID 30791431, 2019). "Preclinical experiments have further suggested that AR activation correlates with the induction of ovarian tumorigenesis and cancer progression as well as chemoresistance in ovarian cancer." (PMID 30791431, 2019). "Accordingly, AR inactivation has the potential of being not only a promising chemopreventive and/or therapeutic approach against ovarian cancer but also a means of chemosensitization, particularly in patients with AR-positive tumor." (PMID 30791431, 2019). "Meanwhile, an increasing amount of evidence has indicated the involvement of AR and related signals in the development and progression of ovarian cancer." (PMID 30791431, 2019). "The AR is known to be expressed in ovarian cancer cells, but little is known about the impact of AR expression and activity on the natural history of the disease." (PMID 34926721, 2019). "Emerging evidence has suggested that androgen receptor signaling plays an important role in ovarian cancer outgrowth." (PMID 30791431, 2019). "Our results from the cell line experiments suggest caution should be used when using AR expression or activity as eligibility criteria for patient selection on clinical trials that are evaluating molecules targeting AR in ovarian cancer." (PMID 34926721, 2019). "Then, western blotting has confirmed AR protein expression in these ovarian cancer primary cultures or cell lines." (PMID 30791431, 2019). "The length of the CAG repeats has been shown to inversely correlate with AR transcriptional activity in various types of cells, including ovarian cancer cells." (PMID 30791431, 2019). "To investigate if such an interaction exists in ovarian cancers, we first treated ovarian cancer cells with metformin and examined the effects on AR activity." (PMID 34926721, 2019). "AR expression and activity were quantified using immunohistochemistry (IHC) and RT-qPCR in six ovarian cancer cell lines and 51 tissue samples." (PMID 34926721, 2019). "The AR is widely expressed in the normal ovarian epithelium and also has been reported to be expressed to varying degrees in ovarian cancer epithelial cells." (PMID 34926721, 2019). "The roles of androgen/AR signaling in ovarian cancer progression have been reported previously, and some therapeutic strategies targeting androgen/AR have been tested either in experimental models or clinical settings." (PMID 30986993, 2019). "Targeting AR with ASC-J9 is thus a potential therapeutic strategy for treating the serous subtype of ovarian cancer." (PMID 30986993, 2019).
ovarian carcinoma (continued). "Although the underlying molecular mechanisms for androgen receptor functions in ovarian cancer remain far from being fully understood, current observations may offer effective chemopreventive and therapeutic approaches, via modulation of androgen receptor activity, against ovarian cancer." (PMID 30791431, 2019). "Emerging evidence has suggested the role of androgen-mediated AR activation in the outgrowth of various types of malignancies, including ovarian cancer." (PMID 30791431, 2019). "The effects of androgen treatment on the cell growth of AR-positive ovarian cancer have been assessed in a substantial number of studies." (PMID 30791431, 2019). "Ovarian cancer cells treated with different hormones were used to confirm the effect of the AR signaling axis." (PMID 29716628, 2018). "The AR signaling axis promotes the proliferation, migration and invasion of ovarian cancer cells in vitro and in vivo and interacts with many key signaling components, including the IL-6/IL-8 and EGFR pathways." (PMID 29716628, 2018). "Meanwhile, emerging evidence has indicated that AR is frequently expressed in various ovarian cancer subtypes, especially epithelial ovarian cancer, and its high expression is associated with a poor prognosis." (PMID 29716628, 2018). "In this study, using luciferase assays, we showed that the AR signaling axis induced Nanog promoter activity in ovarian cancer cells." (PMID 29716628, 2018). "In recent years, the relationship between ovarian cancer and the AR signaling axis has become a popular topic of research because polycystic ovary syndrome and obesity are associated with a high risk of ovarian cance." (PMID 29716628, 2018). "Our results showed that the AR expression levels were significantly higher in ovarian cancer than in normal ovarian tissues." (PMID 29716628, 2018). "Several studies have reported that AR expression is higher in ovarian cancer than in normal ovaries." (PMID 29716628, 2018). "Hence, we hypothesized that the AR signaling axis is associated with ovarian cancer." (PMID 29716628, 2018). "In this study, we have demonstrated that the AR signaling axis induces Nanog-mediated stemness properties and tumorgenicity in ovarian cancer." (PMID 29716628, 2018). "To examine AR expression in ovarian cancer, we compared the AR protein expression levels in ovarian cancer tissues (n = 7) with those in normal ovarian tissues (n = 7) with a western blot analysis." (PMID 29716628, 2018). "After treatment of the ovarian cancer cell lines with the AR inhibitor ASC-J9, the DHT-mediated sphere and colony formation of the ovarian cancer cell lines was diminished." (PMID 29716628, 2018). "Similar results have been obtained in prostate (regulation of enzymes involved in androgen synthesis and modulation of androgen receptor levels and activity) and ovary cancer." (PMID 30386380, 2018). "Since agents used for AR blockade in ovarian cancers are known to be weak AR antagonists, novel promising treatments that are more potent suppressors of the AR axis should be evaluated in clinical trials for ovarian cancers." (PMID 27741511, 2017). "Collectively, these results support the notion that increased AR expression tends to predict a favorable prognosis in epithelial ovarian cancer, especially in serous carcinoma of the ovary." (PMID 27741511, 2017). "Recently, AR was reported to degrade cell cycle inhibitor p27 and down-regulate p21 expression in ovarian cancer." (PMID 27741511, 2017). "AR is highly expressed in ovarian cancers, with approximately 44% to 82% of tumors staining positive for AR." (PMID 28085048, 2017). "In this article, we provide a comprehensive overview on the role of AR in ovarian cancer carcinogenesis and progression." (PMID 27741511, 2017). "As alluded above, in vitro studies have suggested that androgen/AR signaling promotes tumor cell growth, invasion and survival in human ovarian cancer cell lines, which makes targeting AR a promising treatment strategy." (PMID 27741511, 2017).